TH (tyrosine hydroxylase)
Diseases named in the same sentence as TH in open-access papers (continued):
Sharing a sentence is not in itself a finding about the gene and the disease.
migraine (7 papers, 2009 to 2023). "In population 1, a five-marker risk haplotype in the DRD2 gene and a single variant in the TH gene were found to be associated with migraine, and both remained significant after applying correction for multiple comparisons." (PMID 19772578, 2009). "Vitamin D may stimulate serotonin synthesis via tyrosine hydroxylase; hence, vitamin D deficiency may lead to the depression of serotonin synthesis, which is usually observed in tension-type headache and migraine." (PMID 31261815, 2019). "Vitamin D can affect the synthesis of serotonin via tyrosine hydroxylase and subsequently, participate in the occurrence of the comorbidity of migraine and RLS." (PMID 34867766, 2021). "B. Results of the association study of DRD2 rs2283265 and TH rs2070762 in the migraine without aura and migraine with aura subgroups of population 1 and population." (PMID 19772578, 2009).
colitis (6 papers, 2020 to 2024). Inflammation of the colon. "The increased TH expression induced by DSS was dramatically blocked by EA treatment in L6 DRG of colitis rats." (PMID 36910013, 2023). "A key finding in this study is that colitis reduced striatal levels of TH and DAT in males for at least five weeks after the last exposure to DSS." (PMID 34412704, 2021). "Our results demonstrated that DSS colitis upregulated SP, HA, BK, PGI2, and 5-HT expression in the skin and increased TRPV1, TRPA1, and TH in L6 DRG, implying that DSS promoted surface neurogenic inflammation evoked by sympathetic-sensory coupling in skin-DRG." (PMID 36910013, 2023). "In a rat model of trinitrobenzene sulfonic acid- (TNBS-) induced colitis, sympathetic nerve fiber sprout was found in the DRG of the lumbosacral segment (L6, S1), manifested by tyrosine hydroxylase- (TH-) positive nerve fibers increased." (PMID 36910013, 2023). "A decrease in TH, NPY and VIP expressing CaMG-neurons was also presented for chemically induced colitis in pigs." (PMID 34246257, 2021). "TH protein levels were significantly reduced by MPTP in males and females as well as by colitis alone in male mice compared to RGS10+/+ H2O-Saline levels." (PMID 34412704, 2021). "In mice in which CD8+ T-cells had been depleted, DSS colitis did not induce reductions in striatal TH or DAT." (PMID 34412704, 2021). "Since TH catalyzes the rate-limiting step in this synthesis of catecholamines, these results further support the observation that catecholaminergic dysregulation is characteristic for the colonic inflammation observed in TNBS- and DSS-induced colitis." (PMID 34884737, 2021). "Male mice that experienced colitis exhibited sustained reductions in tyrosine hydroxylase but not in dopamine as well as sustained CD8+ T-cell infiltration and elevated Ifng expression in the brain." (PMID 34412704, 2021). "Importantly, the deficiencies in striatal TH and DAT protein levels relative to controls which were induced by DSS colitis were no longer observed after CD8 depletion, implicating cytotoxic T-cells as direct mediators of these effects." (PMID 34412704, 2021).
hypothyroidism (6 papers, 2014 to 2025). Abnormally low levels of thyroid hormone. "This phenomenon has most prominently been observed in rats that were exposed to maternal hypothyroidism during the late stages of embryonic development, with E19 to P2 being an exceptionally sensitive window towards a disruption in TH signaling." (PMID 37569727, 2023). "Induction of hypothyroidism by PTU administration to adult rats resulted in a rise in hypothalamic, cortical, and hippocampal dopamine levels, whereas neonatal hypothyroidism reduced dopamine-producing tyrosine hydroxylase and dopamine turnover in the striatum." (PMID 37569727, 2023). "Although Dio2-KO mice display elevated brain T4 levels and reduced T3 content, surprisingly, the observed neurological impairments, which included changes in the cerebellar expression of TH-dependent genes and behavioral defects, were found to be mild compared with those observed in hypothyroidism." (PMID 24904526, 2014). "Hypothyroidism is diagnosed by serum concentration of TSH above normal (>4.5 mU/L) and that of FT4 below (primary hypothyroidism), although tertiary and secondary hypothyroidism may occur when deficits are at hypothalamic or pituitary levels and both serum TSH and TH concentrations are low." (PMID 34745011, 2021). "However, TRs did not bind to the GnIH promoter region in either case of hypothyroidism or hyperthyroidism, thus TH may act through non-genomic action in GnIH neurons via plasma membrane or cytosol-located TRs41." (PMID 28432332, 2017).
melanoma (6 papers, 2012 to 2024). A malignant, usually aggressive tumor composed of atypical, neoplastic melanocytes. "One plausible explanation for the potential association between melanoma and PD is that α-Synuclein, an enzyme that inhibits tyrosine hydroxylase, is involved in the melanin synthesis in both melanoma and dopaminergic neuronal cells in PD." (PMID 33173642, 2020). "Different from melanoma cells, dopaminergic neuronal cells express mainly TH enzyme involved in the biosynthesis of DA, and accordingly, neuromelanin (NM), melanin presented in dopaminergic neurons." (PMID 23028833, 2012). "Skin conditions, particularly seborrheic dermatitis, rosacea, bullous pemphigoid, and melanoma, each have an increased incidence in PwP and have been attributed to dysregulation of the autonomic nervous system, or to inhibition of tyrosine hydroxylase by α-synuclein." (PMID 38639839, 2024). "Alterations in melanin or dopamine synthesis enzymes, including tyrosinase (TYR) and tyrosine hydroxylase (TH), may also contribute to increased vulnerability to both melanoma and PD." (PMID 37629650, 2023).
psychosis (6 papers, 2012 to 2025). "In humans, this enzyme is encoded by the tyrosine hydroxylase (TH) gene, and this gene plays a significant role in AD progression and the development of psychosis." (PMID 40004081, 2025). "In sum, we identified a decrease in repressive epigenetic marks at an enhancer linked to TH gene regulation in neurons of patients with major psychosis." (PMID 31053723, 2019). "Additionally, a review of various animal models of psychosis showed that dopamine supersensitivity and elevated D2High states, which are often associated with psychosis, are related to increased activity of tyrosine hydroxylase." (PMID 40004081, 2025). "In the context of psychosis in AD, research on spinocerebellar ataxia (SCA) patients with psychosis showed increased TH staining in the substantia nigra, indicating a potential link between elevated dopamine production by TH and the development of psychosis." (PMID 40004081, 2025). "Further study is required to fully characterize the extent to which enhancers regulate TH and dopamine signaling in psychotic disorders." (PMID 31053723, 2019). "In the present study three TH SNPs, i.e. rs10770141, rs10840491 and rs10840489, were associated with HVA concentrations in patients with psychosis." (PMID 25073638, 2014). "Chromosome 11 includes several plausible candidate genes for major psychiatric disorders, especially psychosis, including the tyrosine hydroxylase (TH) and the dopamine receptor D4 (DRD4) (both at 11p15)." (PMID 23300629, 2012). "Here, the authors characterise the hypomethylation of an enhancer within the insulin-like growth factor 2 gene in neurons of patients with major psychosis and provide evidence that this enhancer targets the tyrosine hydroxylase gene, responsible for dopamine synthesis." (PMID 31053723, 2019). "The epigenetic regulatory connection between IGF2 and TH may also help explain the co-occurrence of neuronal structure and synaptic abnormalities with dopamine dysregulation in major psychosis patients." (PMID 31053723, 2019).
Sepsis (6 papers, 2017 to 2026). Sepsis is defined as life-threatening organ dysfunction caused by a dysregulated host response to infection. "The evidently reduced expression of TH in the septic group suggests the “suppression” of catecholaminergic neurons in sepsis." (PMID 39156045, 2024). "Indicative of SNS activation, we found increased levels of tyrosine hydroxylase, an enzyme responsible for noradrenaline production in sympathetic fibers, in the BM after sepsis." (PMID 35192546, 2022). "The inflammation of the central nervous system not only enhances the TH expression but also promote the apoptosis of catecholaminergic neurons; severe apoptosis of catecholaminergic neurons in sepsis gives rise to the reduction of CAP output." (PMID 33061821, 2020). "Due to the downregulation of phenylalanine hydroxylase and tyrosine hydroxylase activities during sepsis, the conversion of phenylalanine and tyrosine to dopamine is blocked, and more phenylalanine and tyrosine may be converted to pseudo-neurotransmitters in the brain, affecting nerve signaling." (PMID 39498415, 2024).
Stroke (6 papers, 2013 to 2024). Sudden impairment of blood flow to a part of the brain due to occlusion or rupture of an artery to the brain. "After stroke, TH-positive neurons were reduced by 33% in the ipsilesional compared to the contralesional midbrain in the control group (ipsi: 1002 ± 315.7 cells, contra: 1496 ± 526.4 cells, n = 6, paired t-test p = 0.0079)." (PMID 35409207, 2022). "To investigate whether stroke induces striatonigral degeneration, we measured the presence of TH-positive (+) fibers and neuronal cells in the striatum and substantia nigra (SN) of the mouse brain following tMCAO." (PMID 39578419, 2024). "In our study, reduced TH and DAT levels were found in the PFC at 8 weeks post stroke, indicating that focal ischemia might cause a chronic impairment on dopaminergic activity in the remote PFC." (PMID 32010477, 2020). "Moreover, significantly reduced expressions of tyrosine hydroxylase (TH), the rate-limiting enzyme in dopamine synthesis, and dopamine transporter (DAT), a key factor in dopamine reuptake, were observed in the PFC of stroke mice." (PMID 32010477, 2020).
tyrosine hydroxylase deficiency (6 papers, 2016 to 2025). "Tyrosine hydroxylase deficiency (THD) is an ultra‐rare autosomal recessive inherited metabolic disorder caused by a deficient cerebral tyrosine hydroxylase enzyme (TH, OMIM 191290)." (PMID 41215497, 2025). "Tyrosine hydroxylase deficiency (THD) is a treatable inborn error of dopamine biosynthesis caused by mutations in TH." (PMID 36101825, 2022). "It was suggested that the accurate clinical diagnosis of TH deficiency should be based on mutation analysis of the TH gene and central catecholamine deficiency, that is, low HVA, low MHPG, low HVA/HIAA ratio, and normal 5-HIAA in CSF." (PMID 34054692, 2021). "Mutations in TH lead to the disease tyrosine hydroxylase deficiency, and TH is also a marker for the dopaminergic neurons that degenerate in Parkinson’s disease." (PMID 27462005, 2016). "Tyrosine Hydroxylase Deficiency (THD) is a rare genetic disorder caused by bi-allelic mutations in the TH gene, which encode for tyrosine hydroxylase (TH) protein." (PMID 37041529, 2023). "Tyrosine hydroxylase deficiency (THD) is a rare movement disorder with broad phenotypic expression caused by bi-allelic mutations in the TH gene, which encode for tyrosine hydroxylase (TH) protein." (PMID 37041529, 2023).
viral infection (6 papers, 2022 to 2025). "Virus infection disrupted the circadian rhythm of tyrosine hydroxylase (Aath), a key dopamine synthesis gene, maintaining its consistent elevation of expression throughout the day." (PMID 40298398, 2025). "For instance, in Bombyx mori, viral infection triggers specific overexpression of TH in the brain, resulting in significantly elevated dopamine levels." (PMID 40906217, 2025). "The magnitude of SNc TH+ neuron reduction increased with the time elapsed following Cre virus infection in the Oxtrflox/flox mice." (PMID 39099429, 2024). "For this purpose, we analyzed the expression of 10 tobacco resistance genes that are triggered by individual virus infection and suppressed by the TH complex." (PMID 37035074, 2023). "Cre virus infection efficiently knocked out oxytocin receptors in the SN of OxtRflox/flox mice at 30 dpi, but did not reduce SNc TH neurons or striatum TH level." (PMID 39099429, 2024).
cyst (5 papers, 2011 to 2025). A sac-like closed membranous structure that may be empty or contain fluid or amorphous material. "Furthermore, we have recently identified an enzyme with tyrosine hydroxylase activity encoded in the Toxoplasma genome whose expression is induced during differentiation to tissue cyst stages." (PMID 21957440, 2011). "It is possible that the tyrosine hydroxylase expression observed within the tissue cyst could be either the T. gondii-encoded tyrosine hydroxylase or neuronal tyrosine hydroxylase that has been imported from the host." (PMID 21957440, 2011). "TH immunoreactivity around the cyst was more abundant in the 12 M group (arrowhead) than in senescent animals (arrowhead)." (PMID 35217964, 2022). "T. gondii is thought to provide excessive levels of tyrosine hydroxylase in the cyst areas, and this enzyme is the rate-limiting factor in dopamine synthesis that becomes increased in such areas." (PMID 35741850, 2022). "Likewise, Afonso and colleagues found that AaaH2 TH deletion did not prevent cyst formation, indicating that this enzyme is not essential, either in sole or part, for in vivo cyst differentiation." (PMID 41350261, 2025). "Moreover, AaaH2 TH deletion did not prevent cyst formation, demonstrating that this enzyme is not necessary for in vivo cyst differentiation, consistent with recent reports for cyst growth in in vitro and in vivo conditions." (PMID 29062106, 2017).
epilepsy (5 papers, 2015 to 2024). A brain disorder characterized by episodes of abnormally increased neuronal discharge resulting in transient episodes of sensory or motor neurological dysfunction, or psychic dysfunction. "Therefore, TH alone could not explain the pathogenicity of YWHAG mutations in epilepsy." (PMID 33767733, 2021).
Insulin resistance (5 papers, 2014 to 2025). Increased resistance towards insulin, that is, diminished effectiveness of insulin in reducing blood glucose levels. "Specifically, insulin resistance has been reported to reduce both nigrostriatal dopamine release and dopamine clearance in the brain, whereas insufficient insulin secretion results in reduced dopamine transporter and tyrosine hydroxylase mRNA in the substantia nigra." (PMID 24806840, 2014).
memory impairment (5 papers, 2021 to 2024). "Consistently, intranasal administration of MCH (0.5 μg in 30 μL saline) significantly recapitulated the acupuncture effects on MPTP‐induced motor deficits, TH loss, and memory impairments." (PMID 39119926, 2024). "This research explores caffeine's modulation of the adenosine A2A receptor (A2AR) and its regulatory effects on tyrosine hydroxylase (TH), aiming to restore dopamine homeostasis and mitigate memory impairments associated with hypoxia." (PMID 39670604, 2024). "As our results, HFD- induced precocious puberty mice have memory impairment in adulthood, and TH, NeuN, AVP in hypothalamus related to cognition and memory are significantly reduced." (PMID 34530850, 2021).
myocardial infarction (5 papers, 2017 to 2024). Gross necrosis of the myocardium, as a result of interruption of the blood supply to the area, as in coronary thrombosis. "Meanwhile, growth-associated protein-43 (GAP-43), a marker of nerve sprouting, and tyrosine hydroxylase (TH), a marker of the sympathetic nerve, were significantly elevated in myocardial infarction mice." (PMID 35178131, 2022). "Studies have found that sympathetic nerve remodeling after MI has been observed in patients with myocardial infarction and animal models, and the densities of TH and GAP43 positive nerve fibers have increased." (PMID 34471416, 2021). "Nori and his colleagues have found that tyrosine hydroxylase (TH) was the majority of regenerated nerve fibers after myocardial infarction, indicating that the regenerated nerves are dominated by mature sympathetic nerves." (PMID 34471416, 2021). "Experimental studies in rats with depression combined with Myocardial Infarction (MI) have shown elevated plasma levels of epinephrine and norepinephrine, along with higher levels of myocardial tyrosine hydroxylase expression compared to the MI-only group." (PMID 38404466, 2024). "In this study, YQHX can significantly regulate nerve remodeling related factors and reduce the protein content of TH, NGF, and GAP43 in the marginal area of infarction and the stellate ganglion in rats with myocardial infarction." (PMID 34471416, 2021). "During the recovery from myocardial infarction, cardiac nerve sprouting and sympathetic hyperinnervation significantly enhanced in the infarcted area, manifested with the increased numbers of both GAP-43 and TH positive nerves in the CB, IBZ and LVFW of the MI animals." (PMID 28732009, 2017).
anxiety disorder (4 papers, 2019 to 2024). A category of psychiatric disorders which are characterized by anxious feelings or fear often accompanied by physical symptoms associated with anxiety. "The dopaminergic upregulation mediated by tyrosine hydroxylase activity of T. gondii may increase the risk of other disorders of lower ORs like obsessive compulsive disorder, antisocial personality disorder, and anxiety disorder." (PMID 32132937, 2019). "Several DEGs shared by the male Tg and NTg have previously been linked to early-life stress, anxiety disorders and ADHD (Erbin), sex-specific gene expression in ASD and dopamine changes (Erbb2ip, Neurod6), and to TH-dependent growth and embryonic differentiation processes (Secisbp2l)." (PMID 34100083, 2021).
Cerebral ischemia (4 papers, 2008 to 2020). Restriction of arterial blood supply to the brain associated with insufficient oxygenation to support the metabolic requirements of the tissue. "Enhancing the activity of tyrosine hydroxylase and increasing the synthesis of endogenous dopamine can effectively improve the nerve function of rats after cerebral ischemia/reperfusion injury." (PMID 33328857, 2020). "These outcomes are in line with previous reports of enlarged granular TH terminals and large synaptophysin-positive dots after cerebral ischemia/reperfusion in the rat CPu." (PMID 31920641, 2019). "MCAO treatment significantly increased TH-positive expression after a 36-h cerebral ischemia/reperfusion injury (p < 0.05)." (PMID 31920641, 2019). "The result of tyrosine hydroxylase in this study is consistent with those of other studies, that is, the dopamine level in the hippocampus decreased and was lower than the normal level after cerebral ischemia/reperfusion injury." (PMID 33328857, 2020). "Immunohistochemical and immunofluorescence analyses revealed high level of tyrosine hydroxylase (TH) in the ipsilateral striatal caudate putamen (CPu) after cerebral ischemia/reperfusion, which could be further elevated by salidroside." (PMID 31920641, 2019). "This study clarifies the neuroprotective effects of edaravone (MCI-186, 3-methyl-1-phenyl-2-pyrazolin-5-one), which has already been used for the treatment of cerebral ischemia in Japan, on TH-positive dopaminergic neurons using PD model both in vitro and in vivo." (PMID 18671880, 2008).
Huntington disease (4 papers, 2013 to 2022). Huntington disease (HD) is a rare neurodegenerative disorder of the central nervous system characterized by unwanted choreatic movements, behavioral and psychiatric disturbances and dementia. "The neuronal markers that we validated here for GABAergic (GAD67+) and dopaminergic (tyrosine hydroxylase+) neurons, have been used to document imbalanced signaling associated with learning and memory deficits in NF1 and with other cognitive and motor impairments in Huntington’s disease." (PMID 32074109, 2020).